PSMC2 (proteasome 26S subunit, ATPase 2)
Diseases named in the same sentence as PSMC2 in open-access papers (continued):
Sharing a sentence is not in itself a finding about the gene and the disease.
ovarian carcinoma (10 papers, 2017 to 2024). A malignant neoplasm originating from the surface ovarian epithelium. "Collectively, knockdown of PSMC2 caused a loss in cell growth and cell migration ability of ovarian cancer cells." (PMID 34294689, 2021). "Similarly, PSMC2, a key member of the 19 S RP, has been implicated in the progression of several types of cancer, including ovarian cancer, pancreatic cancer, and osteosarcoma." (PMID 38243058, 2024). "In this study, we found that PSMC2 was upregulated in ovarian cancer tissues, associated with tumor grade and could probably predict poor prognosis." (PMID 34294689, 2021). "For instance, PSMC2, the most investigated one, has been found to be upregulated in various types of cancer, including gastric cancer, ovarian cancer, and hepatocellular carcinoma, promoting tumor cell proliferation and invasion." (PMID 36699466, 2022). "For example, the expression of PSMC2 increased in tumors of p21-HBx transgenic mice and downregulation of PSMC2 inhibited the proliferation of ovarian cancer cells." (PMID 33902600, 2021). "For further exploring the role of PSMC2 in the development of ovarian cancer, we injected HO-8910 cells transfected with shPSMC2 or shCtrl subcutaneously into nude mice for developing xenografts." (PMID 34294689, 2021). "Survival analysis based on data collected from TCGA indicated the potential linkage between PSMC2 high expression and poor prognosis of patients with ovarian cancer." (PMID 34294689, 2021). "PSMC2 suppression decreased cell proliferation in ovarian cancer and was also correlated with pancreatic cancer cell proliferation and apoptosis." (PMID 34716318, 2021). "CCND1, also known as cyclin D1, was identified as a potential downstream of PSMC2, which regulate the development of ovarian cancer in together with PSMC2." (PMID 34294689, 2021). "Next, we carried out a loss-of-function study through downregulating the endogenous expression of PSMC2 in ovarian cancer cell lines HO-8910 and OVCAR-3 based on lentivirus criteria." (PMID 34294689, 2021). "The outcomes of the IHC staining demonstrated the obvious upregulation of PSMC2 in ovarian cancer tissues." (PMID 34294689, 2021). "In conclusion, a novel tumor promotor PSMC2 was identified in ovarian cancer, which is upregulated in ovarian cancer, accelerating cell proliferation and colony formation, promoting cell migration, inhibiting cell apoptosis and predicting poor prognosis." (PMID 34294689, 2021). "This study was accomplished for the purpose of getting insight into the role and mechanism of PSMC2 in ovarian cancer development." (PMID 34294689, 2021). "In the mechanistic study on PSMC2-induced cell apoptosis, Bcl-w, which has been well-documented to be a mediator in the regulation of ovarian cancer, was found to be downregulated upon PSMC2 knockdown." (PMID 34294689, 2021). "First of all, the expression of PSMC2 was evaluated in ovarian cancer tissues, followed by a comparison with that in normal tissues to initially investigate the possible involvement of PSMC2 in ovarian cancer." (PMID 34294689, 2021). "In the current study, we identified PSMC2 as a critical regulator of the ovarian cancer development and progression." (PMID 34294689, 2021). "Data collected from TCGA database also potentiate the relationship between PSMC2 level and poor prognosis of patients with ovarian cancer." (PMID 34294689, 2021). "Studies have shown that in ovarian cancer cells, inhibiting PSMC2 expression can inhibit cell proliferation." (PMID 32972417, 2020). "Nijhawan first disclosed that the therapeutic efficacy of PSMC2 suppression for ovarian cancer in vivo." (PMID 27888613, 2017). "First, we evaluated the expression levels of the six PSMC family members in 24 types of cancer in TCGA database and found that PSMC5 was the most predominant in all types of cancer except ovarian cancer, whereas PSMC2 and PSMC6 had a relatively lower expression level in pan-cancer." (PMID 36699466, 2022).
ovarian carcinoma (continued). "Inhibition of PSMC2 expression is able to inhibit the proliferation of ovarian cancer cells." (PMID 35287689, 2022). "Altogether, we believe that PSMC2 may regulate the development of ovarian cancer in combination of CCND1." (PMID 34294689, 2021). "Moreover, although no normal tissue samples are available in TCGA database, the survival analysis based on the features of 377 ovarian cancer patients built the linkage of PSMC2 high expression and poor prognosis of patients." (PMID 34294689, 2021). "Ovarian cancer tissues possess relatively higher expression of PSMC2 than normal tissues." (PMID 34294689, 2021). "Knocking down the endogenous PSMC2 expression in ovarian cancer cells could decrease colony formation ability, cell motility and cell proliferation rate, along with increasing cell apoptosis rate." (PMID 34294689, 2021). "Consequent upon findings mentioned, PSMC2 may have a critical regulatory function in the development and progression of ovarian cancer." (PMID 34294689, 2021). "In vitro and in vivo assays elucidated that silencing PSMC2 could significantly inhibit ovarian cancer development through regulating cell growth, apoptosis and migration." (PMID 34294689, 2021). "High PSMC2 expression also predicts more advanced tumor grade of ovarian cancer." (PMID 34294689, 2021). "Moreover, gene microarray was used to analyze the alteration of gene expression profiling of ovarian cancer induced by PSMC2 knockdown and identify CCND1 as a potential downstream of PSMC2." (PMID 34294689, 2021). "We observed higher expression of PSMC2 in ovarian cancer tissues than normal tissues." (PMID 34294689, 2021). "Bearing all these in mind, we hypothesized that CCND1 may serve as a potential downstream target of PSMC2 in the regulation of ovarian cancer." (PMID 34294689, 2021). "In a word, our work identified PSMC2 as a critical participate in ovarian cancer development, which could be a target for diagnosis or treatment of ovarian cancer." (PMID 34294689, 2021). "In ovarian cancer cells, reduction of PSMC2 expression inhibited cell proliferation." (PMID 31598166, 2019). "Indeed, the authors showed that PSMC2 suppression decreases ovarian cancer cell proliferation and its expression also correlated with pancreatic cancer cell proliferation." (PMID 31598166, 2019). "However, the relationship between PSMC2 and ovarian cancer has been seldom studied and remained unknown." (PMID 34294689, 2021). "Moreover, preliminary mechanistic study revealed that PSMC2 may execute its regulatory effects on ovarian cancer in combination with CCND1." (PMID 34294689, 2021). "Furthermore, reduction expression of PSMC2 inhibited ovarian cancer cells proliferation." (PMID 27888613, 2017). "Loss-of-function assays performed on ovarian cancer cells with or without PSMC2 knockdown illustrated that PSMC2 may promote the progress of ovarian cancer by means of promoting cell proliferation, colony formation, cell migration and alleviating cell apoptosis." (PMID 34294689, 2021). "Although the role of CCND1 in ovarian cancer has been well described, its synergistic effect with PSMC2 has not been investigated." (PMID 34294689, 2021). "In summary, PSMC2 may promote the development of ovarian cancer through CCND1, which may predict poor prognosis of ovarian cancer patients." (PMID 34294689, 2021). "Our study further indicated that the combined inhibition targeting PSMC2 and CCND1 may be an effective treatment strategy for ovarian cancer." (PMID 34294689, 2021). "PSMC2 is an essential component of 19 S regulatory granules in 26 S proteasome and its relationship with ovarian cancer is still not clear." (PMID 34294689, 2021). "Moreover, considering that CCND1 plays essential roles in current therapeutic strategies for ovarian cancer patients that involve platinum therapy and checkpoint inhibitors, the exploration of the functions of PSMC2 and CCND1 in ovarian cancer should be of great significance." (PMID 34294689, 2021).
ovarian carcinoma (continued). "In addition, PSMC2 may regulate ovarian cancer through CCND1, knockdown of both in combination could induce intense inhibition effects on the development and progression of ovarian cancer." (PMID 34294689, 2021).
glioma (7 papers, 2022 to 2025). A benign or malignant brain and spinal cord tumor that arises from glial cells (astrocytes, oligodendrocytes, ependymal cells). "The survival rate of patients with high expression of PSMC2 was significantly lower than that of patients with low expression, indicating that PSMC2 is an independent risk factor affecting the survival time of glioma patients." (PMID 35287689, 2022). "A newly identified gene, proteasome 26S subunit ATPase 2 (PSMC2), has been linked to the pathogenesis of multiple cancers, including gliomas." (PMID 36425564, 2022). "PSMC2 has been implicated as an oncogene in multiple cancer types, including glioma, gastric cancer, squamous cell carcinoma, and skin cutaneous melanoma, to name a few." (PMID 36498916, 2022). "Through the RNA-Seq data of TCGA (The Cancer Genome Atlas) and GTEX (Genotype-Tissue Expression), we found that PSMC2 was significantly upregulated in glioma and was associated with patient survival." (PMID 35287689, 2022). "Elevated expression of PSMC2 has been observed in gliomas and is associated with a poor prognosis for patients with this disease; inhibition of PSMC2 can inhibit the cancer progression and drug resistance through regulation of immune microenvironment and cell autophagy." (PMID 41318472, 2025). "Through ROC curve analysis, PSMC2 was identified as a potential diagnostic marker of glioma." (PMID 35287689, 2022). "We find that PSMC2, with high expression in glioma cells, is essential for the survival of glioma cells and for the proliferation and apoptosis of glioma cells." (PMID 35287689, 2022). "PSMC2 promotes the proliferation of glioma cells and inhibits the apoptosis, which is expected to be a potential therapeutic target for glioma." (PMID 35287689, 2022). "The results identified that PSMC2 affected the apoptosis pathway, which further clarified the mechanism of PSMC2 in glioma." (PMID 35287689, 2022). "The results of Western blot and qRT-PCR showed that PSMC2 was significantly overexpressed in glioma tissues." (PMID 35287689, 2022). "According to RNA-Seq data from 163 glioma patients downloaded from TCGA, we performed enrichment analysis based on the co-expression genes of PSMC2 in tumor tissues." (PMID 35287689, 2022). "In this study, the proliferation ability of glioma cells decreased significantly after PSMC2 knockdown and so of the apoptosis ability of glioma cells as evaluated by the Annexin V-FITC/PI apoptosis assay." (PMID 35287689, 2022). "It suggests that the high expression of PSMC2 in glioma can inhibit apoptosis and promote cell proliferation and can be used as a therapeutic target for glioma." (PMID 35287689, 2022). "Western blot results showed that PSMC2 was significantly overexpressed in glioma samples (p < 0.05)." (PMID 35287689, 2022). "Annexin V-FITC/PI apoptosis assay was used to detect the effect of PSMC2 knockdown on the apoptosis ability of glioma cells." (PMID 35287689, 2022). "This study aims to investigate the effect of PSMC2 expression on the clinical prognosis of glioma patients and its molecular mechanism." (PMID 35287689, 2022). "According to the RNA-Seq data of 163 glioma patients downloaded from TCGA, we enriched and analyzed the co-expression genes of PSMC2 in tumor tissues." (PMID 35287689, 2022). "Through broad-spectrum screening of 31 kinds of tumors, we found that PSMC2 was upregulated in most tumors, but PSMC2 was most significantly overexpressed in gliomas and correlated with poor prognosis in glioma patients." (PMID 35287689, 2022). "Western blot and qRT-PCR results of clinical samples showed that PSMC2 was highly expressed in glioma tissues, and its expression level increased with the increase of tumor malignancy." (PMID 35287689, 2022). "In order to evaluate PSMC2 expression in different glioma cell lines, we measured PSMC2 mRNA levels in 7 glioma cell lines (AM38, A172, LN229, U118MG, U87MG, U251MG, and U343MG) by RT-qPCR." (PMID 35287689, 2022).
glioma (continued). "PSMC2 was found to be upregulated in osteosarcoma, prostate cancer, pancreatic cancer, glioma, oral squamous cell carcinoma (OSCC), and hepatocellular carcinoma (HCC)." (PMID 35938038, 2022). "The results determined that the expression level of PSMC2 was significantly correlated with the overall survival rate and disease-free survival rate of glioma patients." (PMID 35287689, 2022). "Through broad-spectrum screening of several tumors, PSMC2 was upregulated in most of them, but it was most significantly overexpressed in gliomas and correlated with poor prognosis in glioma patients." (PMID 36425564, 2022). "The results indicate that inhibiting the expression of PSMC2 can promote the apoptosis of glioma cells." (PMID 35287689, 2022). "RT-qPCR showed that the higher the malignant degree of glioma, the higher the expression level of PSMC2." (PMID 35287689, 2022). "In this study, we used TCGA database to analyze the expression of PSMC2 in 31 kinds of tumors and found significantly upregulated PSMC2 in four tumors, especially glioma (GBM and LGG)." (PMID 35287689, 2022). "The measurement of PSMC2 expression in glioma tissues and control tissues revealed that PSMC2 was highly expressed in GBM (p < 0.001) and LGG (p < 0.05) tissues, and GBM was the most significant." (PMID 35287689, 2022). "Based on cell proliferation and apoptosis experiments, we speculated that high levels of PSMC2 may be conducive to the proliferation or survival of cancer cells in the tissue samples of glioma patients." (PMID 35287689, 2022). "PSMC2 expression in glioma and normal tissues was detected by Western blot and RT-qPCR." (PMID 35287689, 2022). "Additionally, knockdown of PSMC2 in a glioma cell line inhibited proliferation and affected apoptosis, supporting it as a relevant tumor biomarker." (PMID 36425564, 2022). "Therefore, this study aims to explore the effect of PSMC2 expression on glioma and its molecular mechanism." (PMID 35287689, 2022). "Hence, PSMC2 plays a role in the apoptosis of glioma by acting on the Bcl-2/Bax/cleaved caspase-3 apoptosis signaling pathway." (PMID 35287689, 2022). "To further analyze the detailed mechanism of PSMC2 affecting apoptosis process in glioma cell lines, we designed the following experiment to test whether PSMC2 expression affects the levels of apoptosis-related proteins." (PMID 35287689, 2022). "Therefore, we hypothesized that PSMC2 expression can be used as a biomarker to predict the prognosis of patients with glioma." (PMID 35287689, 2022). "Therefore, it can be reasonably speculated that PSMC2 may play a tumor-promoting role in gliomas through apoptosis pathway." (PMID 35287689, 2022). "Thus, PSMC2 may be a potential target for the treatment of glioma." (PMID 35287689, 2022). "To date, however, there are no reports about the expression of PSMC2 in broad-spectrum tumors and its effect on the survival of patients, especially on gliomas." (PMID 35287689, 2022). "To verify whether PSMC2 affects the growth of glioma cells, we performed a CCK-8 assay to evaluate the proliferation of glioma cells after PSMC2 knockdown." (PMID 35287689, 2022). "Among them, IFNGR2, TXLNA, PSMC2, and TMSB15A have not been reported to be associated with gliomas." (PMID 37867596, 2023).
pancreatic cancer (7 papers, 2019 to 2024). "PSMC2 is highly expressed in pancreatic cancer, and PSMC2-knockdown significantly decreased cell proliferation." (PMID 34329194, 2021). "A survival analysis showed that the OS of high expression PSMC2 in colorectal cancer samples was lower than that with low expression PSMC2, and patients with pancreatic cancer who expressed high PSMC2 had a poor prognosis." (PMID 34716318, 2021). "A similar function of PSMC2 as tumor promotor was also observed in pancreatic cancer and colorectal cancer." (PMID 34244472, 2021). "Materials and Methods: Quantitative RT-PCR (qRT-PCR) was performed to assess mRNA expression levels of PSMC2 in different pancreatic cancer cell lines." (PMID 31598166, 2019). "In the same study, PSMC2 expression also reportedly correlated with pancreatic cancer cell proliferation." (PMID 31598166, 2019). "The effects of PSMC2 silencing on pancreatic cancer cell proliferation and apoptosis were evaluated by the MTT cell proliferation assay, Celigoassays, Annexin V fluorescence-activated cell sorting (FACS) assay and Caspase-3/7 array." (PMID 31598166, 2019). "We first assessed PSMC2 mRNA levels in a panel of different pancreatic cancer cell lines (SW1990, PANC-1 and AsPC-1) using qRT-PCR." (PMID 31598166, 2019). "Here, we report, for the first time, the effects of PSMC2 on pancreatic cancer cell proliferation and apoptosis." (PMID 31598166, 2019). "Using RNA interference, we found that PSMC2 was necessary for proliferation and also suppressed apoptosis of pancreatic cancer cells." (PMID 31598166, 2019). "Understanding the precise role of PSMC2 in pancreatic cancer pathogenesis will be critical and might facilitate the development of anti-tumor therapies against PSMC2." (PMID 31598166, 2019). "Then, we demonstrated that PSMC2 expression was critical for pancreatic cancer cell survival." (PMID 31598166, 2019). "In conclusion, our study for the first time revealed an important function of PSMC2 in mediating proliferation and apoptosis in pancreatic cancer, and suggested that PSMC2 might serve as a potential therapeutic target for the treatment of pancreatic cancer." (PMID 31598166, 2019). "However, whether PSMC2 carries out the similar functions in pancreatic cancer remains unexplored." (PMID 31598166, 2019).
colorectal cancer (6 papers, 2020 to 2022). A primary or metastatic malignant neoplasm that affects the colon or rectum. "PSMC2, located in the genome 7q22.1 – q22.3, was highly expressed in colorectal cancer, suggesting a poor prognosis." (PMID 35256584, 2022). "Loss of NAT2, a non-essential enzyme involved in drug metabolism, in colorectal cancers emerged as an attractive target conceptually different from synthetic lethality (ENO2, PRMT5, ME3) or targeting genes essential for cell survival (POLR2A, RPA70, or PSMC2)." (PMID 32161261, 2020).
hepatocellular carcinoma (6 papers, 2017 to 2022). A malignant tumor that arises from hepatocytes. "Recently, the research found that Psmc2 expression is upregulated in tumor tissues of p21-HBx transgenic mice, thereby enhancing the ubiquitin-proteasome and lysosomal pathways and contributing to the development of HBx-associated hepatocellular carcinoma." (PMID 35237384, 2022). "Upregulation of PSMA6, PSMB4, PSMC2 and PSMD12 was also observed in hepatocellular carcinomas in p21-HBx transgenic mice." (PMID 27966459, 2017).